NGF (nerve growth factor)
Diseases named in the same sentence as NGF in open-access papers (continued):
Sharing a sentence is not in itself a finding about the gene and the disease.
pheochromocytoma (continued). "Nerve growth factor (NGF)-differentiated PC12 pheochromocytoma cells are frequently used." (PMID 33854099, 2021). "A model for this study, the PC12 cell line, derived from a pheochromocytoma of the rat adrenal medulla, is often used in evaluation of neurotoxicity and neuroprotective effects of different compounds, particularly after Nerve Growth Factor (NGF)-induced differentiation." (PMID 32260390, 2020). "NS-1 cells are a subclone of the PC12 cell line and are NGF-responsive pheochromocytoma cells." (PMID 32059349, 2020). "PC12 cells originated from rat pheochromocytoma could be differentiated into neuron‐like cells in response to nerve growth factor (NGF)." (PMID 30712312, 2019). "Stimulation of PC12 (rat adrenal pheochromocytoma) cells with NGF is known to activate the MAPK." (PMID 24752675, 2014). "Therefore, we used PC12 cells, a widely used rat pheochromocytoma cell line that responds to nerve growth factor (NGF) and acquires many of the characteristics of sympathetic neurons." (PMID 18483549, 2008). "When nerve growth factor (NGF) is applied to PC-12 cells, (a rat pheochromocytoma cell line), ERK3 level is increased." (PMID 38611058, 2024). "For example, in the PC12 cell line derived from a pheochromocytoma from rat adrenal glands, ERK is transiently activated in a pulsatile manner upon stimulation by EGF, while it sustains the up-regulated state of the nerve growth factor (NGF)." (PMID 35050327, 2022). "Nerve growth factor (NGF) induces sustained Erk1/2 activation and neurite outgrowth of PC12 adrenal pheochromocytoma cells." (PMID 31651330, 2019). "S100A10 is induced by nerve growth factor, and increased S100A10 levels promote the proliferation of PC12 cells, a pheochromocytoma cell line." (PMID 22206547, 2011). "In cultured rat pheochromocytoma cells, some authors observed that GLP-1 and exendin-4, (Ex-4) a long-acting GLP-1 analogue, stimulated neurite outgrowth in a similar fashion to nerve-growth-factor (NGF)." (PMID 21747826, 2011). "VGSCs have been found to be regulated by growth factors, such as fibroblast growth factor (FGF), nerve growth factor (NGF), epidermal growth factor (EGF), in various human and rat cell lines, such as pheochromocytoma PC12 cells and rat PCa Mat-LyLu cells." (PMID 18036246, 2007). "K252a is a serine/threonine protein kinase inhibitor (IC50s of 10 to 30 nM) that has been shown to block neuronal differentiation in rat pheochromocytoma cells and is also a potent inhibitor (IC50 of 3 nM) of tyrosine protein kinase activity of the nerve growth factor trk oncogene." (PMID 36139553, 2022). "Therefore, we examined the interactions of adiponectin and SPARC with NGF using a surface plasmon resonance (SPR) method and their effects on NGF-dependent morphological changes in PC12 rat pheochromocytoma." (PMID 30934765, 2019). "Constitutive expression of NeuroD6 triggers neuronal differentiation of PC12 cells, originated from a pheochromocytoma of the rat adrenal medulla, without requirement of nerve growth factor (NGF)." (PMID 25548427, 2014). "We have established a human pheochromocytoma precursor cell line that expresses the neuroendocrine marker, chromogranin A, when differentiated in the presence of bone morphogenic protein 4 (BMP4), nerve growth factor (NGF), and dexamethasone." (PMID 23785438, 2013). "We used infected non-polarized and polarized PC12 cells, a rat pheochromocytoma cell line that acquires many of the characteristics of sympathetic neurons in the presence of nerve growth factor (NGF)." (PMID 18483549, 2008). "Similarly, nerve growth factor (NGF) stimulation of PC-12 pheochromocytoma cells as opposed to epidermal growth factor (EGF) stimulation leads to sustained high-level ERK1/2 activation and not a proliferative, but a differentiation response." (PMID 22784513, 2012).
pancreatic cancer (74 papers, 2008 to 2026). "The overexpression of NGF can cause the hyperplasia of nerves, leading to an increase NI of pancreatic cancer cells." (PMID 39723256, 2024). "It has been reported that signaling from the nerve growth factor (NGF) pathway associated with peripheral nerves is able to contribute to perineural invasion (PNI) of pancreatic cancer (PC)." (PMID 36285300, 2022). "NGF genes overexpress along with TrkA in pancreatic cancer tissue compared with normal pancreatic tissue, and increased NGF / TrkA expression is associated with invasion and pain caused by tumors." (PMID 32986378, 2020). "Signaling via the nerve growth factor (NGF) pathway between pancreatic cancer cells and the surrounding nerves has been implicated in PNI, and increased levels of these proteins have been correlated to poor prognosis." (PMID 27792755, 2016). "Similarly, in pancreatic cancer, NE derived from sympathetic nerves causes overexpression of NGF and MMPs, leading to PNI development." (PMID 39906323, 2024). "Specifically, mice develop increased microvascular density, NGF-expressing macrophages and sensory and sympathetic innervation to the pancreas at 6 weeks following the induction of the pancreatic cancer model—all pathological events that are linked to precancerous cellular abnormalities." (PMID 36688083, 2022). "Because, we speculated that NGF/TrkA promoted neuroinvasion in pancreatic cancer may be associated with upregulation of miR-21-5p by NGF." (PMID 36285300, 2022). "However, more work needs to be done to understand the underlying mechanism of NGF signaling mediated perineural invasion in pancreatic cancer." (PMID 27792755, 2016). "Indeed, in malignant melanoma, expression of CD271 has been associated with PNI, and in oral cancer and pancreatic cancer, the expression of NGF has also been associated with PNI." (PMID 25149537, 2014). "For instance, nerve growth factor (NGF) stimulates sensory fibers located in the dorsal root ganglia, which plays a crucial role in the pain experienced by individuals with pancreatic cancer." (PMID 41601691, 2026). "This phenomenon extends to breast, gastric, and pancreatic cancers, where NGF secretion drives axonogenesis and facilitates neural network formation within tumors, highlighting the crucial role of NGF in the construction of neural networks within tumors." (PMID 41556039, 2026). "Pancreatic cancer cells typically exhibit high levels of NGF, and knocking down TrkA can inhibit PNI in these cells." (PMID 40421086, 2025). "In pancreatic cancer, the NGF/TrkA pathway enhances PNI by promoting the Warburg effect and upregulating the expression of miR-21-5p." (PMID 40421086, 2025). "Given our previous report that NGF expression in pancreatic tumor cells is induced by β-adrenergic stimulation through the MAPK pathway, we examined this possibility for NTN1 expression." (PMID 40777309, 2025). "NGF is secreted by pancreatic cancer cells and TME-resident stromal cells, including tumor-associated immune cells and cancer-associated fibroblasts." (PMID 39119085, 2024). "Upregulated NGF can bind to its receptors TrkA and p75NTR on pancreatic cancer cells and nerve cells, facilitating cancer cell migration and invasion as well as nerve cell survival, growth and development." (PMID 39119085, 2024). "It has been shown that pancreatic cancer cells with little serine can selectively increase the translation of the nerve growth factor (NGF), which, in turn, recruits axons as an exogenous source of serine." (PMID 38791953, 2024). "In turn, the expression of NGF can decrease the apoptosis of pancreatic cancer cells due to the collective signalling of NGF and TrkA in pancreatic cancer." (PMID 39723256, 2024). "Concurrently, pancreatic cancer cells regulate neuronal growth and amino acid release by secreting NGF and IGF-1, establishing a comprehensive feedback loop." (PMID 38567163, 2024).
pancreatic cancer (continued). "Within pancreatic cancer cells, there is secretion of the Nerve Growth Factor (NGF) and axon guidance molecule SEMA3D." (PMID 38567163, 2024). "The findings of a study indicate that the use of gold nanoclusters to assist in the delivery of siRNA targeting NGF (GNC–siRNA) is a highly effective approach for silencing the NGF gene and treating pancreatic cancer." (PMID 37242788, 2023). "This complex significantly reduced tumor formation in three pancreatic tumor models by knocking down NGF expression (subcutaneous, orthotopic, and patient-derived xenograft models)." (PMID 37981671, 2023). "It was further confirmed that the expression of nerve growth factor (NGF) receptor in human pancreatic cancer has prognostic value." (PMID 38041128, 2023). "First, NGF secretion was measured by ELISAs in the serum-free medium of five pancreatic cancer cell lines." (PMID 35109895, 2022). "Using both in vivo and in vitro models, studies revealed a critical involvement of assorted neural pathways, such as substance P (SP)/NK-1R, NGF and β-adrenergic signals in pancreatic cancer PNI." (PMID 35954387, 2022). "We further confirmed NGF expression in human pancreatic cancer tissues by showing that NGF expression was also higher in tissues with PNI." (PMID 35449152, 2022). "Immunofluorescence results showed that NGF expression was reduced in pancreatic cancer cells after Nodal knockdown, and these results were consistent with western blot results." (PMID 35126957, 2022). "In conclusion, our study has provided evidence supporting that the HGF/c-Met signaling pathway promotes PNI in pancreatic cancer by activating the mTOR/NGF axis and increasing the invasion and migration ability of pancreatic cancer cells." (PMID 35449152, 2022). "SCs displayed tropism to pancreatic tumour cells, at least in part dependant on the NGF-p75 signalling." (PMID 35269454, 2022). "In mouse models of pancreatic cancer, extensive sprouting of sensory and sympathetic fibres is also detected and partly attributed to the high levels of NGF released by the cancer cells and/or the inflammatory cells." (PMID 36688083, 2022). "Taken together, our findings suggest a supportive mechanism of the HGF/c-Met signaling pathway in promoting PNI by activating the mTOR/NGF axis in pancreatic cancer." (PMID 35449152, 2022). "A similar effect of NGF-TrkA pathway in other GI tumors, such as colorectal and pancreatic cancers, has also been observed." (PMID 35954387, 2022). "Previous studies showed that co-culture of Schwann cells with pancreatic cancer cells increased NGF production by Schwann cells." (PMID 36522730, 2022). "Mechanistically, HGF/c-Met signaling pathway can active the mTOR/NGF axis to promote the PNI of pancreatic cancer." (PMID 35449152, 2022). "The GNC-siRNA efficiently downregulated the NGF expression in Panc-1 cells, pancreatic tumors, and further inhibited the tumor progression in three pancreatic tumor models." (PMID 35200353, 2022). "Recent studies showed that NGF accelerated the development of gastric tumorigenesis, pancreatic cancer, liver cancer, head and neck squamous cell carcinoma, prostate cancer, and chondrosarcoma." (PMID 36522730, 2022). "In the present study, we revealed that mTOR can regulate NGF expression as an upstream regulator in pancreatic cancer." (PMID 35449152, 2022). "In genetically engineered mice harboring spontaneous pancreatic cancer, the suppression of NGF signaling slows the development of pancreatic disease." (PMID 35449152, 2022). "Perineural invasion is common in pancreatic cancer cells correlating to poor prognosis and can be facilitated by nerve growth factor." (PMID 34195085, 2021). "In pancreatic cancer, adrenergic signaling to tumor cells induces nerve growth factor (NGF) and brain-derived neurotrophic factor (BDNF) release by tumor cells, resulting in increased nerve density in the tumor area." (PMID 33466373, 2021).
pancreatic cancer (continued). "NGF has been reported to be highly expressed in pancreatic tumors and to be able to promote the migration and invasion of human pancreatic cancer cells." (PMID 34777634, 2021). "The gold nanocluster-assisted delivery of NGF targeting siRNA (GNC-siRNA) allowed efficient NGF gene silencing and pancreatic tumor treatment in subcutaneous, orthotopic, and patient-derived xenograft models." (PMID 34683931, 2021). "The inhibition of NGF by blocking STAT3 resulted in decreased pancreatic cancer migration and reduced perineural invasion." (PMID 34195085, 2021). "In fact, ADRB2 is significantly upregulated in these genetically engineered pancreatic cancer mouse models, thereby increasing NGF and BDNF production, stimulating NGF/Trk pathways and enhancing pancreatic nerve density." (PMID 34439102, 2021). "Dorsal root ganglion (DRG) and pancreatic cancer cell co-culture models suggested that a mutual tropism exists between the nerves/DRGs and pancreatic cancer cells through multiple molecular factors (e.g., NGF-TRKA pathway)." (PMID 33392191, 2020). "Of note, NGF depletion by anti–NGF antibodies or gene silencing with gold nanoclusters siRNA reduces progression, metastasis and pain in several pre–clinical models of pancreatic tumors." (PMID 31248001, 2019). "The use of nanocluster-associated delivery of siRNA against NGF represents an innovative way to target and inhibit NGF expression specifically in PDAC, as demonstrated in mouse models where it inhibited pancreatic tumor progression." (PMID 30741921, 2019). "As a further confirmation of the role of these molecules in pancreatic cancer, high levels of NGF and TrKA correlate with increased frequency and severity of PNI as well as reduced survival and increased pain in patients." (PMID 31248001, 2019). "Depending on expression levels and the ratio of TrkA to p75NTR, NGF can have either stimulatory or inhibitory effects; this indicates communication between pancreatic cancer cells secreting NGF and surrounding nerves expressing both p75NTR and TrkA68." (PMID 30741921, 2019). "In human specimens, the levels of mast cell degranulation products, including tryptase, histamine, and NGF, were found to be significantly increased in tissues surrounding pancreatic carcinoma relative to those in normal pancreatic tissues." (PMID 31201657, 2019). "The tP19 is a pancreatic cancer-specific aptamer, while NGF siRNA is a known inhibitor of pancreatic cancer progression." (PMID 30274155, 2018). "Nerve growth factor (NGF) contributes to the sustained growth and metastasis of pancreatic cancer cells." (PMID 28440296, 2017). "Our study constitutes a straightforward but effective approach to inhibit pancreatic cancer via NGF knockdown, suggesting a promising therapeutic direction for pancreatic cancer." (PMID 28440296, 2017). "Together, GNC-assisted delivery of NGF siRNA is a promising therapeutic approach for pancreatic cancer treatment by targeting the interactions between the tumours and the nervous microenvironment." (PMID 28440296, 2017). "The GNC–siRNA complex potently knocked down the NGF expression in pancreatic cells and in pancreatic tumours, and effectively suppressed the pancreatic tumour progression via NGF knockdown." (PMID 28440296, 2017). "To conclude, we have developed biocompatible GNCs as a delivery platform for siRNA (GNC–siRNA complex) to target the tumour–neuron interaction for pancreatic cancer treatment via NGF depletion." (PMID 28440296, 2017). "To assess the relevance of innervation in human pancreatic cancer, we analysed the NGF expression and neurite distribution in human pancreatic tumours from pancreatic cancer patients." (PMID 28440296, 2017). "We confirmed the distribution of NGF protein in orthotopic pancreatic tumours by IF staining, where the NGF level was markedly suppressed by GNC–siRNA group compared to the saline control." (PMID 28440296, 2017).
pancreatic cancer (continued). "Herein, we developed GNCs for efficient delivery of NGF siRNA (GNC–siRNA) to silence NGF gene in pancreatic cancer, aiming to inhibit pancreatic cancer progression." (PMID 28440296, 2017). "Here, the authors develop a gold nanocluster-coupled siRNA against NGF that efficiently silences the NGF gene and inhibits tumour growth of pancreatic cancer in mice." (PMID 28440296, 2017). "Together, the analysis of the biopsies revealed the widespread expression of NGF protein and abundant neurites in human pancreatic tumours, suggesting that targeting NGF is promising for pancreatic cancer treatment." (PMID 28440296, 2017). "The statistical analysis of western blotting indicated a significantly higher expression of NGF in pancreatic tumour tissues than in normal pancreas (P<0.01, n=4)." (PMID 28440296, 2017). "Immunohistochemistry (IHC) and immunofluorescence (IF) assays of NGF confirmed that the pancreatic tumours exhibited significantly higher NGF immunoreactivity compared to normal pancreas." (PMID 28440296, 2017). "Elevated levels of NGF in pancreatic cancer cells and high levels of its receptors, TRKA and p75NTR in the surrounding nerves, have been correlated to poor prognosis and PNI in pancreatic cancer patients." (PMID 27792755, 2016). "A deeper understanding of this NGF signaling pathway will aid in designing novel therapeutics that prevent PNI and alleviate pain associated with PNI in patients with pancreatic cancer." (PMID 27792755, 2016). "In this study, we examine the molecular mechanism of the NGF signaling pathway in PNI in pancreatic cancer." (PMID 27792755, 2016). "Here we have demonstrated that NGF signaling via TRKA between pancreatic cancer cells and surrounding nerves is one of the molecular mechanisms involved in PNI." (PMID 27792755, 2016). "NGF is also involved in regulating tumour growth and progression of cancers including lung, medullar thyroid carcinoma, prostatic, breast and pancreatic carcinomas." (PMID 27875990, 2016). "The clinical association observed in the current study is supported by the previously reported experimental evidence that hyperglycemia was related to a higher expression of NGF and neurotrophic factors in pancreatic cancer cells and nerve fibers." (PMID 23342285, 2012). "NGF has previously been shown to be a direct mitogenic factor in pancreatic cancer and presumably influences perineural cancer invasion and metastatic spread." (PMID 20978507, 2010). "Because of the in vivo observation that PHD3 immunoreactivity was strongly stained next to nerves in pancreatic cancer we determined the role of NGF in PHD3-mediated apoptosis, as previous reports indicated that NGF influences apoptosis." (PMID 20978507, 2010). "Nerve growth factor (NGF) not only promotes nerve tissue growth, development and regeneration, but regulates the growth and metastasis of pancreatic cancer, prostate cancer, lung cancer and retinal glioblastoma cells." (PMID 18983683, 2008). "In pancreatic tumors, cancer cells secrete NGF to recruit nerve fibers into TME." (PMID 41556039, 2026). "Additionally, NGF acts as a key driver of neuroinflammation in the tumor microenvironment of pancreatic cancer, and its inhibition can significantly reduce tumor-associated PNI and alleviate cancer-related pain." (PMID 40421086, 2025). "Sympathetic neurotransmitter norepinephrine (NE) activates the ADRB2/PKA/STAT3 signaling pathway, leading to an increase in pancreatic cancer cell expression of NGF, MMP2, and MMP9, thereby enhancing their migration, invasion, and nerve infiltration capabilities." (PMID 38567163, 2024). "Both pancreatic cancer cells and pancreatic stellate cells are capable of secreting NGF." (PMID 38567163, 2024). "Pancreatic cancer exhibits a significant upregulation of the nerve growth factor (NGF) gene." (PMID 39128942, 2024).